CEBPZ (CCAAT enhancer binding protein zeta)
Description:
Stimulates transcription from the HSP70 promoter.
Synonyms: CBF; CBF2; CTF2; HSP-CBF; NOC1
Tractability: PROTAC: ubiquitination databases record sites on it; its protein half-life has been measured.
Gene: Protein-coding gene on chromosome 2 (37,201,570 to 37,231,601, reverse strand). Ensembl gene ENSG00000115816.
Subcellular location: Nucleus
Subcellular location (Human Protein Atlas): Nucleoplasm; Vesicles
Gene Ontology:
Molecular function: DNA binding; protein binding; RNA binding; transcription coactivator activity
Biological process: positive regulation of transcription by RNA polymerase II
Cellular component: nucleoplasm; nucleus; CCAAT-binding factor complex
Genetic constraint (gnomAD): Loss-of-function variants: 55 observed, 74.63 expected, observed/expected ratio (o/e) 0.74, 90% interval 0.59 to 0.92. The upper end of that interval is the gene's LOEUF score, 0.92, which puts it in group 3 of 6, group 1 being the genes least tolerant of losing a copy. Missense variants: 1,251 observed, 1,102.6 expected, observed/expected ratio (o/e) 1.13, 90% interval 1.08 to 1.19. Synonymous variants: 423 observed, 391.77 expected, observed/expected ratio (o/e) 1.08, 90% interval 1 to 1.17.
Homologues: Orthologues: chimpanzee CEBPZ (99% identical), macaque CEBPZ (96% identical), dog CEBPZ (88% identical), rabbit CEBPZ (87% identical), pig CEBPZ (86% identical), guinea pig CEBPZ (82% identical), mouse Cebpz (82% identical), rat Cebpz (81% identical), tropical clawed frog cebpz (57% identical), zebrafish cebpz (53% identical), Drosophila melanogaster Noc1 (28% identical), Caenorhabditis elegans F23B12.7 (27% identical), and 1 more.
Diseases named in the same sentence as CEBPZ in open-access papers:
CEBPZ is named in the same sentence as 20 diseases in open-access papers, as found by Europe PMC text mining. Sharing a sentence is not in itself a finding about the gene and the disease. The quoted sentences say what the papers report.
acute myeloid leukemia (11 papers, 2009 to 2025). Acute myeloid leukemia (AML) is a group of neoplasms arising from precursor cells committed to the myeloid cell-line differentiation. "In tumors, CEBPZ has been proposed as a marker for colorectal and gastric cancers, whereas point and missense mutations have been identified in individuals with acute myeloid leukemia (AML), where CEBPZ works as a cofactor to maintain m6A modifications in leukemia cells." (PMID 40827841, 2025). "CEBPZ has been demonstrated to recruit METTL3 to genes essential for acute myeloid leukaemia such that it can induce m6A modifications that aid their translation." (PMID 33846365, 2021). "CEBPZ expression and methylation have been remarkably correlated with acute myeloid leukemia." (PMID 36553500, 2022). "Notably, in acute myeloid leukemia (AML), CEBPz was shown to promote the m6A modification of target mRNA transcripts, enhancing their translation." (PMID 38213308, 2023). "Furthermore, in acute myeloid leukemia (AML), METTL3, operating independently of METTL14, is recruited to chromatin by the CAATT-box binding protein CEBPZ and localizes to the transcription start site to regulate the translation of target genes." (PMID 38444581, 2024).
adenoma (1 paper, 2025). A neoplasm arising from the epithelium. "The transcriptional co-regulatory mechanisms pathway was identified, exhibiting DEGs in the adenocarcinoma cohorts compared to adenoma; these genes include CEBPZ, MED10 and PAWR." (PMID 40362431, 2025). "ARRB1 (p = 2.79 × 10−5), CTBP1 (p = 1.33 × 10−5) and CTBP2 genes (p = 0.0002) exhibited notable upregulation in adenoma, whereas COL1A2 (p = 0.0075), CEBPZ (p = 0.0057), MED10 (p = 0.0196) and PAWR genes (p = 0.00215) showed significant upregulation in adenocarcinoma." (PMID 40362431, 2025).
Cirrhosis (1 paper, 2024). A chronic disorder of the liver in which liver tissue becomes scarred and is partially replaced by regenerative nodules and fibrotic tissue resulting in loss of liver function. "Additionally, upregulated TF activities in MYOFIB/HSC were noted for PATZ1 in preneoplastic stages (e.g., Cirrhosis, AK, and CAG), while CEBPZ and SOX6 demonstrated elevated activities in malignant (e.g., cSCC and HCC) stages." (PMID 38645221, 2024).
kidney cancer (1 paper, 2025). Primary or metastatic malignant neoplasm involving the kidney. "Further investigation of the co-expression dynamics of these genes in kidney cancers and Pearson correlation analysis revealed a consistently strong positive correlation between CEBPZ and NOC3L across all kidney tumor types, suggesting potential co-regulation." (PMID 40827841, 2025). "These distinct patterns suggest a possible dual behavior of the NOC proteins in kidney cancers – whereas CEBPZ and NOC3L might function cooperatively, NOC2L might act independently or even antagonistically in certain contexts." (PMID 40827841, 2025). "Among kidney cancer subtypes, chromophobe renal cell carcinomas (KICH) showed consistently and significantly reduced expression levels of CEBPZ, NOC2L and NOC3L, whereas other subtypes, such as KIRC (clear cell) and KIRP (papillary), displayed more variable expression patterns." (PMID 40827841, 2025).
kidney chromophobe carcinoma (1 paper, 2025). "Expression profiling across diverse tumor types revealed distinct patterns for CEBPZ, NOC2L and NOC3L, with them being elevated in several cancers, yet markedly reduced in AML and kidney chromophobe carcinoma (KICH)." (PMID 40827841, 2025). "In contrast, there was an inverse correlation between CEBPZ and NOC3L expression and outcomes in kidney chromophobe carcinoma." (PMID 40827841, 2025).
kidney tumors (1 paper, 2025). "To deeply investigate the co-expression patterns of CEBPZ, NOC2L and NOC3L within kidney tumors, we analyzed the TCGA datasets publicly accessible through FireBrowse." (PMID 40827841, 2025).
liver carcinoma (1 paper, 2025). An epithelial or non-epithelial malignant neoplasm that arises from the liver.
osteoporosis (1 paper, 2023). A condition of reduced bone mass, with decreased cortical thickness and a decrease in the number and size of the trabeculae of cancellous bone (but normal chemical composition), resulting in increased fracture incidence. "The network based on hub genes showed that 3 TFs (TRIM22, CEBPG, and CEBPZ), 4 miRNAs (hsa-miR-132-3p, hsa-miR-182-5p, hsa-miR-212-3p, and hsa-miR-324-5p), and 4 drugs were involved in osteoporosis." (PMID 38260098, 2023).
renal carcinoma (1 paper, 2025). A carcinoma arising from the epithelium of the renal parenchyma or the renal pelvis. "In contrast, in KIRC and KIRP renal carcinomas, although the expression of CEBPZ was low, that of NOC2L and NOC3L increased." (PMID 40827841, 2025). "A Pearson correlation coefficient was calculated between the expression of the three genes (CEBPZ, NOC2L and NOC3L) in the three kidney carcinoma subtypes (KICH, KIRC, and KIRP)." (PMID 40827841, 2025). "Additionally, CEBPZ, NOC2L, and NOC3L exhibited distinct expression patterns during the progression of kidney carcinoma, with a marked decrease observed in KICH." (PMID 40827841, 2025).
tumor (7 papers, 2010 to 2025). "Functional analysis confirmed that ARRB1 and CTBP1/2 were associated with early tumor development, while COL1A2 and CEBPZ were involved in extracellular matrix remodeling and transcriptional regulation, respectively." (PMID 40362431, 2025). "Moreover, comparative analysis of TCGA datasets from tumor databases revealed that CEBPZ, NOC2L and NOC3L exhibit contrasting expression patterns across tumor types." (PMID 40827841, 2025). "Notably, TNMplot analysis in an independent CRC cohort revealed a significant upregulation of CEBPZ expression in tumor-stage CRC compared to normal and metastatic tissues." (PMID 40362431, 2025). "We analyzed the expression across diverse tumor types based on the hypothesis that CEBPZ, NOC2L and NOC3L form regulatory heterodimers that modulate this process." (PMID 40827841, 2025). "We then examined CEBPZ, NOC2L and NOC3L expression patterns across various stages of tumor development using TGCA datasets from the UALCAN portal." (PMID 40827841, 2025). "Preliminary data on the human homolog CEBPZ, along with studies of NOC2L and NOC3L expression in tumor datasets, suggest that these proteins have conserved roles in ribosome biogenesis across species." (PMID 40827841, 2025). "Finally, we analyzed the correlation between the expression of CEBPZ, NOC2L and NOC3L and survival for individuals with cancer to explore their potential impact on disease outcomes across tumor types." (PMID 40827841, 2025).
cancer (4 papers, 2019 to 2025). A tumor composed of atypical neoplastic, often pleomorphic cells that invade other tissues. "Differential expression of CEBPZ, NOC2L and NOC3L across cancer types with varying prognostic implications implies tissue-specific or context-dependent roles." (PMID 40827841, 2025).
adenocarcinoma (1 paper, 2025). A common cancer characterized by the presence of malignant glandular cells. "In adenocarcinoma, COL1A2, CEBPZ, MED10 and PAWR were overexpressed, suggesting their involvement in advanced disease progression." (PMID 40362431, 2025). "In adenocarcinoma samples, key upregulated candidate biomarkers include COL1A2, CEBPZ, MED10 and PAWR." (PMID 40362431, 2025).
genetic disorder (1 paper, 2023). "This, together with other indirect information on the potential role of NOC1/CEBPz in controlling alternative splicing, highlights the potential role of the human counterpart in the control of nucleolar processes that may cause genetic disorders." (PMID 38213308, 2023).
CEBPZ also shares sentences with these, for which no sentence is quoted: infection (3 papers); leukaemia (2); adenoid cystic carcinoma (1); Cognitive impairment (1); colon cancer (1); gastric cancer (1); rectum adenocarcinoma (1).